IL6 (interleukin 6)
Diseases named in the same sentence as IL6 in open-access papers (continued):
Sharing a sentence is not in itself a finding about the gene and the disease.
rhegmatogenous retinal detachment (3 papers, 2012 to 2024). Retinal detachment secondary to retinal tear or break. "Another study also found that some inflammatory factors (IL-8 and IP-10) were increased in the aqueous humor of post-vitrectomy eyes in rhegmatogenous retinal detachment patients, whereas other factors (IL-6 and MCP-1) remained unchanged." (PMID 34568366, 2021). "In another control group of rhegmatogenous retinal detachment, the concentrations of most cytokines showed low values except IL-6, IL-8, and VEGF." (PMID 23049699, 2012).
salmonellosis (3 papers, 2018 to 2025). Infections with bacteria of the genus salmonella. "In salmonellosis, there is often an increase in levels of pro-inflammatory cytokines like interleukins (IL-1 and IL-6), TNF-α, and interferon-gamma (IFN-γ)." (PMID 38667028, 2024).
salpingitis (3 papers, 2012 to 2024). Acute or chronic inflammation of the fallopian tube. "Recently, Wang and co-authors proposed a model connecting ADM, interleukin-6, and -8 with increasing risk of ectopic pregnancies in females with fallopian tube inflammation (salpingitis)." (PMID 39682722, 2024). "We found that serum TNF-α and IL-6 were expressed significantly higher in patients with salpingitis and tubal pregnancy, which supported previous studies." (PMID 31088412, 2019). "Serum levels of BAFF, TNF-α and IL-6 were significantly higher in salpingitis group or in tubal pregnancy group when compared to control group (P < 0.01)." (PMID 31088412, 2019). "In this study, serum levels of BAFF, TNF-α and IL-6 were all significantly increased in patients with salpingitis and tubal pregnancy in comparison to control group." (PMID 31088412, 2019). "We found statistically significantly elevated expressions of BAFF mRNA or protein in whole tissue samples, and serum levels of BAFF, TNF-α and IL-6 in whole blood samples from patients with salpingitis and tubal pregnancy, in comparison to the control group." (PMID 31088412, 2019).
seborrheic dermatitis (3 papers, 2023 to 2025). A chronic, inflammatory skin disorder that affects the scalp, central face and skin folds; it is characterized by scaling and itching. "The ELISA analysis revealed that miRNA transfection significantly modulated IL-6, MMP-9, and TNF-α expression levels compared to the control condition, highlighting their therapeutic potential for seborrheic dermatitis." (PMID 40227405, 2025).
selenium deficiency (3 papers, 2017 to 2021). A nutritional deficiency disease resulting from inadequate selenium levels in the body, which can lead to impaired function of selenoproteins essential for antioxidant defense and thyroid hormone metabolism. "Selenium has been found to downregulate the IL-6 response and selenium deficiency has been noted to be associated with higher levels of IL-6 in the elderly." (PMID 32992282, 2020).
sensitization (3 papers, 2015 to 2024). "Th2 cells produce IL-4, IL-5, IL-6, and IL-10, mediate humoral immunity, and are closely associated with the development of hypersensitivity reactions." (PMID 35419003, 2022). "Cockroach allergen can induce mucosal allergic sensitization and inflammation via PAR-2, induce expression of inflammatory cytokine (e.g., IL-8, IL-6), and trigger innate immune response in the human airway epithelium." (PMID 25303775, 2015).
skin sensitization (3 papers, 2012 to 2024). An immunological response to previous exposure to a substance which results in an inflammatory skin reaction. "Our results suggest that the mechanical cue-mediated modulation of focal adhesion proteins and actin cytoskeleton translates into intracellular signaling associated with the IL-6 production particularly in skin sensitization." (PMID 30914685, 2019).
stomatitis (3 papers, 2024 to 2026). Inflammation of the oral mucosa due to local or systemic factors. "This confirmed the presence of a positive feedback regulatory loop between Th17 cells and neutrophils in stomatitis and revealed the critical role of the IL-6-Th17-neutrophil axis in the pathogenesis of stomatitis." (PMID 41459159, 2025). "The stomatitis/EA group suppressed the expression of inflammatory cytokine mRNA, such as Tnf-α and Il-6, and Cox-2 mRNA in the wound area compared with the stomatitis/PS group." (PMID 39570913, 2024). "Il-6 mRNA was significantly upregulated in the stomatitis/PS group; however, it decreased in the stomatitis/EA group (p = 0.0596)." (PMID 39570913, 2024). "Taking these findings together, GL at low concentrations may effectively prevent stomatitis by inhibiting the IL-6-mediated inflammatory pathway." (PMID 41544038, 2026). "In the stomatitis-initiation model, low concentrations of GL (0.0065% and 0.033%) significantly decreased the edema score and histologically reduced the numbers of vessels and neutrophils, as well as the mRNA expression levels of interleukin-6 and cyclooxygenase-2." (PMID 41544038, 2026). "Stomatitis increases neuronal-derived SP release, which upregulates downstream pro-inflammatory cytokine expression (TNF-α and IL-6) and increases COX-2 expression, which enhances PG production." (PMID 39570913, 2024). "Furthermore, we analyzed the expression of Tnf-α and Il-6 mRNA as the inflammation-related genes and Cox-2 and Bdkrb1 mRNA as the pain-related genes in wound tissue through qPCR to determine whether EA suppresses stomatitis pain." (PMID 39570913, 2024).
subacute thyroiditis (3 papers, 2014 to 2022). Self-limited inflammation of the thyroid gland characterized by the presence of multinucleated giant cells. "Several studies demonstrate that IL-6 and IL-8 levels are significantly higher in patients with subacute thyroiditis when compared to normal healthy controls." (PMID 36231061, 2022). "However, in contrast to the present study, patients with subacute thyroiditis present with systemic inflammation, which generates an inflammatory signal mediated by IL-6 that raises hepcidin." (PMID 31700042, 2019).
substance abuse (3 papers, 2013 to 2025). The use of a drug for a reason other than which it was intended or in a manner or in quantities other than directed. "Neuroinflammation, characterized by microglial activation and increased pro-inflammatory cytokines (such as IL-1β, IL-6, and TNF-α), is a potential mechanism behind the behavioral changes observed in individuals exposed to chronic stressors and substance abuse." (PMID 40563776, 2025). "Certain data were not collected including substance abuse, mental health as well as specific biomarkers such as cholesterol, D–dimer, cystatin C and IL–6 all of which have been found to predict HIV treatment outcomes among older adults in western cohorts." (PMID 24098434, 2013). "In the high-quality studies with subjects not using antidepressants, 12/16 (75%) for IL-6 and 5 of 7 studies (71%) for CRP had excluded patients with previous/current substance abuse." (PMID 26065825, 2015).
Takotsubo syndrome (3 papers, 2021 to 2025). "IL-6 is implicated in the production of vasopressin which could explain the higher level of co-peptin in AMI compared to the lower levels seen in Takotsubo syndrome as the levels of IL-6 are much lower in Takotsubo syndrome, as discussed already." (PMID 34095448, 2021). "The IL-6 level is 18.3 ± 5.17 in Takotsubo syndrome and 6.5 ± 5.838 in healthy controls." (PMID 34095448, 2021). "IL-2, IL-4, IL-10, IFN-γ and TNF-α at admission were shown to be significantly higher in patients with acute Takotsubo syndrome compared to patients with AMI, conversely, IL-6 was much higher in AMI patients." (PMID 34095448, 2021). "Additionally, serum interleukin-6 and chemokine (C-X-C motif) ligand 1 concentrations as well as classic CD14++CD16 monocytes are increased, whereas intermediate CD14++CD16+ and non-classic monocytes are reduced in patients with takotsubo syndrome." (PMID 35344411, 2022).
Telangiectasia (3 papers, 2025). Telangiectasias refer to small dilated blood vessels located near the surface of the skin or mucous membranes, measuring between 0.5 and 1 millimeter in diameter. "Elevated IL-6 and HIF-1α further linked hypoxia to vascular alterations, with HIF-1α correlating with telangiectasia." (PMID 41373451, 2025).
thyroid nodule (3 papers, 2020 to 2024). A small circumscribed mass in the THYROID GLAND that can be of neoplastic growth or non-neoplastic abnormality. "Therefore, through transcriptomics in conjunction with literatures, we speculated that JJJG may treat thyroid nodules via (IL-6, TNF-α, IL-1β)/JAK2/STAT3/VEGF pathway." (PMID 39494342, 2024). "Key genes involved in thyroid nodules pathogenesis and JJJG treatment were revealed, such as Il6, Il1b, Jak2, Stat3 and Vegfa, etc.." (PMID 39494342, 2024). "Meanwhile, this study is the first to explore and suggest that the (IL-6, TNF-α, IL-1β)/JAK2/STAT3/VEGF signaling pathway may be involved in regulating the development of thyroid nodules and is one of the possible therapeutic targets for JJJG." (PMID 39494342, 2024). "In a clinical study, 1800 patients with thyroid disease were divided into a thyroid nodule group and a non-nodule group, and serum levels of inflammatory factors such as IL-6 and TNF-α were measured, and regression analysis showed a positive correlation between thyroid nodules and IL-6 and TNF-α." (PMID 39494342, 2024). "Transcriptomics suggested that the (IL-6, TNF-α, IL-1β)/JAK2/STAT3/VEGF pathway may be one of the key mechanisms in the treatment of thyroid nodules by JJJG." (PMID 39494342, 2024). "This study indicates that JJJG efficiently ameliorates thyroid nodules by regulating the levels of FT3, FT4 and TSH in serum and suppressing (IL-6, TNF-α, IL-1β)/JAK2/STAT3/VEGF pathway in thyroid tissue, providing a potential therapeutic approach for thyroid nodules." (PMID 39494342, 2024).
tongue cancer (3 papers, 2017 to 2025). A malignant neoplasm affecting the tongue. "Our findings demonstrate the tumour-promoting effects of adipocytes on tongue cancer cells, suggesting IL-6 and EVs as one of the mediators of these effects." (PMID 41271789, 2025). "However, more research is needed to demonstrate the effects of adipocyte-derived IL-6 (for example by conditional knockout of IL-6 production in adipocytes) or inhibition of EV secretion on tongue cancer progression in in vivo animal experiments." (PMID 41271789, 2025). "At proteomic level, TBM-02 cell line supernatant demonstrated distinct levels of cytokines IL-6 and IL-8, and growth factors EGF, PECAM-1 and VEGF in comparison to AW13516 which is a tongue cancer cell line." (PMID 41410801, 2025). "TPL suppressed the expression of cytokines IL-6, IL-8, and TNF-α and repressed tumor growth, invasion, migration, and angiogenesis in co-inoculation of human tongue cancer cells with macrophage-like U937 cells." (PMID 27073100, 2017). "TPL suppressed the expression of cytokines IL-6, IL-8, and TNF-α, as well as tumor growth, invasion, migration, and angiogenesis in the co-inoculation of human tongue cancer cells with macrophage-like U937 cells." (PMID 27073100, 2017).
toxicity (3 papers, 2008 to 2022). The degree to which an agent can damage an organism. "Increased serum concentrations of IL-6 were significantly associated with higher grade of acute genitourinary toxicity (b = 0.018; p = 0.039)." (PMID 33149212, 2020). "In most of the 21 patients suffering lung toxicity, IL-6 and TGF-β1 plasma levels measured at the onset of RP were increased compared to their individual pre-RT values (in 17 out of 21 patients for IL-6 [81.0%]; in 15 out of 21 patients for TGF-β1 [71.4%]) (data not shown)." (PMID 18682839, 2008).
transverse myelitis (3 papers, 2017 to 2023). "Tocilizumab has improved neurological symptoms in a patient with ICI-related steroid-refractory transverse myelitis with high levels of IL-6 in the CSF and demonstrated efficacy in patients with ICI-mediated cerebritis." (PMID 35043373, 2022). "Higher IL-6 levels were observed in the serum and CSF samples of patients with NMO and transverse myelitis than in the other groups." (PMID 37175665, 2023).
trichomoniasis (3 papers, 2011 to 2025). An infection that is caused by Trichomonas. "The adhesion of Tv to vaginal epithelial cells is pivotal in the pathogenesis of trichomoniasis, facilitating the production of pro-inflammatory cytokines such as IL-8, CCL2, and IL-6." (PMID 40813994, 2025). "For exampleMIP-1α, VEGF and MPO levels were significantly different than controls inChlamydia and trichomoniasis but not BV while in contrast,IL-6, IL-10, GM-CSF, G-CSF, IL-3, IL-7 and IL-12 were significantly changed inChlamydia and BV but not trichomoniasis." (PMID 21572958, 2011).
trypanosomiasis (3 papers, 2024 to 2025). Infection with protozoa of the genus trypanosoma. "The parasite clearance from circulation in trypanosomiasis predominantly relies on antibody-mediated phagocytosis, the production of pro-inflammatory cytokines such as TNF-α, IL-1, and IL-6, as well as the release of nitric oxide by classically activated macrophages." (PMID 40571943, 2025).
tuberculoid leprosy (3 papers, 2016 to 2021). A principal or polar form of leprosy in which the skin lesions are few and are sharply demarcated. "Our previous studies on stable tuberculoid leprosy had indicated that IL-23 and IL23R but not IL-6 and its receptor (IL-6R) were associated with Th17 cell differentiation." (PMID 27035913, 2016).
tuberous sclerosis complex (3 papers, 2017 to 2024). "For example, IL-6 is significantly upregulated and plays a critical role in the development of tuberous sclerosis complex, a benign tumor syndrome caused by aberrant mTORC1 activation due to the loss of either TSC1 or TSC2." (PMID 38610018, 2024).
Tumor Lysis Syndrome (3 papers, 2017 to 2022). a group of metabolic abnormalities that can occur as a complication during the treatment of cancer, most commonly after the treatment of lymphomas and leukemias. "In fact, the increases in the inflammatory cytokines, and IFN-γ and IL-6 coincide with the onset of the tumor lysis syndrome after modified T cell infusion." (PMID 29268708, 2017). "Thus, as in tumor lysis syndrome, serum calcium levels were negatively correlated with plasma levels of CRP, LDH, interleukin-6, and procalcitonin, which support viral replication, development of a cytopathic effect, and subsequent cell death." (PMID 37551398, 2022). "Interestingly, Pt #17 showed low levels of IFNG, IL6, IL1B, C-reactive protein (CRP) and Ferritin, suggesting the grade 3 CRS might be attributed to tumor lysis syndrome or other inflammation pathways." (PMID 34518515, 2021).
type 2 diabetic nephropathy (3 papers, 2019 to 2025). "Our present observations suggest febuxostat suppresses urinary albumin and glomerular injury at early stages of type 2 diabetic nephropathy, i.e., at the stage when inflammatory cytokines, such as IL-6 and MCP-1, are secreted." (PMID 31546603, 2019).
unstable angina pectoris (3 papers, 2014 to 2022). "Some studies suggest that inflammation may promote PC mobilization after acute ischemic events: CRP(C-reactive protein) correlates with the number of endothelial PCs in patients with unstable angina pectoris and interleukin-6 (IL-6) stimulates endothelial PCs at least in vitro." (PMID 24599235, 2014).
vascular hypertrophy (3 papers, 2017 to 2025). "The increases in IL-6 and superoxide have been shown to impact both vascular function and vascular hypertrophy." (PMID 29186034, 2017).
venous ulcers (3 papers, 2020 to 2025). "Experimental animal model studies of wound healing have suggested that IL-6 is essential for wound healing, but conversely high IL-6 levels in exudates from venous ulcers have been associated with poor healing outcomes." (PMID 34104801, 2020). "Notably, the concentration ranges of TNF-α (0 to 2 ng ml−1), TGF-β1 (0 to 150 pg ml−1), IL-8 (0 to 30 ng ml−1), and IL-6 (0 to 30 ng ml−1) were based on levels reported in wound fluids from patients with venous ulcer, combined with ELISA results from clinical samples used for this study." (PMID 34020961, 2021). "As an example of potential clinical application, the VeCare device was applied to assay TNF-α, IL-6, IL-8, TGF-β1, S. aureus, and pH in wound fluids collected from five patients with active venous ulcers, once a week for five consecutive weeks." (PMID 34020961, 2021).
viral hemorrhagic fever (3 papers, 2011 to 2015). A viral infectious disease caused by RNA viruses in the Arenaviridae, Bunyaviridae, Filoviridae, or Flaviviridae family, and characterized by a severe multisystem syndrome, with damage to the vascular system and hemorrhaging. "The observed cytokine responses would be expected to give rise to lymphohistocytosis (often associated with CCHF), while both IL-6 and TNFα are associated with the increase in endothelial permeability that is common in viral hemorrhagic fevers." (PMID 23083136, 2012). "This study suggested that modulation of the amount of IL-6 and TNF-α can have a positive effect on patients with viral hemorrhagic fevers." (PMID 26226614, 2015). "In contrast, the absence of IL-6 and TNF-α production after infection with JUNV might allow the virus to continue to replicate unchecked and thereby achieve the high virus loads and broad tissue dissemination that are indicative of many viral hemorrhagic fevers." (PMID 21572983, 2011).
Waldenström macroglobulinemia (3 papers, 2014 to 2022). "In B-cell malignancy, Waldenstrom Macroglobulinemia (WM), CCL5 modulated IL6 expression through the JAK/STAT signaling pathway." (PMID 25072326, 2014).
xanthoma (3 papers, 2014 to 2022). A non-neoplastic disorder characterized by a localized collection of histiocytes containing lipid. "Indeed, an increased concentration of tryptase, TNF-α, IL-8 and IL-6 in plasma from FH subjects with xanthoma as compared to subjects without xanthoma has been previously reported." (PMID 35897824, 2022).
abnormal glucose tolerance (2 papers, 2021 to 2022). "The level of TNF-α in patients with abnormal glucose tolerance increases significantly; IL-6 can control the signal transduction of insulin receptor and reduce insulin sensitivity." (PMID 35399678, 2022). "It has been demonstrated that the increased level of blood glucose promotes a sharp increase in the concentrations of inflammatory cytokines, such as interleukin-6, tumor necrosis factor α, and interleukin-18, and this effect was more pronounced in subjects with abnormal glucose tolerance." (PMID 35059413, 2021).
Acute bronchitis (2 papers, 2024). Inflammation of the large airways of the lung with rapid onset and short course usually associated with cough, mucus production, shortness of breath, wheezing, and chest tightness. "As summarized in chapter 4.2.1, in vitro and in vivo data indicated that various cytokines and inflammatory mediators were inhibited by DCQAs including IL-6 and TNFα, which seem to play a role during acute bronchitis." (PMID 39239645, 2024).
acute chest syndrome (2 papers, 2024). A vaso-occlusive crisis of the pulmonary vasculature occurring in patients with sickle cell disease. "Their study highlighted that elevated IL-6 levels were associated with a higher risk of developing acute chest syndrome, indicating the importance of early markers in managing crises." (PMID 39449937, 2024).
acute cholangitis (2 papers, 2016 to 2019). Cholangitis that is both sudden in onset and of a relatively short duration. "The injured biliary epithelial cells then secrete proinflammatory and chemotactic cytokines, such as TNF-α and IL-6, causing acute cholangitis, ductular reaction and finally biliary fibrosis." (PMID 26967735, 2016).
acute cholecystitis (2 papers, 2011 to 2025). "Biliary HAMP expression is stress-inducible, in that it increased after IL-6 stimulation and during acute cholecystitis." (PMID 21283681, 2011). "Biliary HAMP is stress-inducible, in that it is increased in biliary cell lines upon IL-6 stimulation and in gallbladder mucosa of patients with acute cholecystitis." (PMID 21283681, 2011).